MMP8 (matrix metallopeptidase 8)
Diseases named in the same sentence as MMP8 in open-access papers (continued):
Sharing a sentence is not in itself a finding about the gene and the disease.
MMP8 also shares sentences with these, for which no sentence is quoted: chronic periodontitis (43 papers); idiopathic pulmonary fibrosis (11); acute myocardial infarction (4); unstable angina (4); Prediabetes (3); apical periodontitis (2); benign neoplasm (2); Chronic Hepatitis C (2); dissection (2); glioma (2); latent infections (2); lymph node (2); nasopharyngeal carcinoma (2); pancreatitis (2); psoriatic arthritis (2); renal cell carcinoma (2); Respiratory distress (2); retinopathy (2); small vessel stroke (2); synovitis (2); thyroid cancer (2); abdominal aortic aneurysm (1); Acne Inversa (1); Acute hepatitis (1); acute lung injury (1); acute lymphocytic leukemia (1); acute respiratory failure (1); adenomyosis (1); aggressive periodontitis (1); Airway obstruction (1).
A further 88 diseases each share a sentence with MMP8 in 1 paper.